ERBB2 (erb-b2 receptor tyrosine kinase 2)
Diseases named in the same sentence as ERBB2 in open-access papers (continued):
Sharing a sentence is not in itself a finding about the gene and the disease.
ductal carcinoma in situ (171 papers, 2004 to 2026). "These phenotypes resemble those observed in ductal carcinoma in situ and also those caused by ErbB2 activation and may explain the high tumorigenic potential of LMW-E over EL." (PMID 22479189, 2012). "Activation of HER2/ErbB2 coincides with escape from ductal carcinoma in situ (DCIS) premalignancy and disrupts 3D organization of cultured breast-epithelial spheroids." (PMID 37055441, 2023).
gastric tumors (157 papers, 2010 to 2026). "The co‐amplification and co‐overexpression of PGAP3 and ERBB2 implicated their potential role in gastric tumour pathogenesis." (PMID 37386793, 2023). "Here, we validate ErbB2 as an in vivo molecular carrier of both α2,3- and α2,6-sialylated N-glycan structures in gastric tumor clinical specimens." (PMID 33947960, 2021). "Another option in the treatment of GEJ tumors and tumors of the stomach with ErbB2 amplification is the combination of ICIs (pembrolizumab and trastuzumab) in addition to 5 fluorouracil/platinum-containing chemotherapy." (PMID 34503263, 2021). "Overexpression of ERBB2 has been reported in multiple cancers, including breast, ovarian, and gastric tumors." (PMID 33004987, 2020). "In the present study, the ERBB2 protein was expressed in 42.0% (29/69) of gastric tumors, and ERBB2 gene amplification occurred in 20.3% (14/69) of tumors." (PMID 21689422, 2011). "ERBB2 amplification was detected in 8 gastric tumor tissues (5.23%)." (PMID 31164161, 2019). "Of the 69 gastric tumors, 14 (20.3%) cases exhibited ERBB2 gene amplification." (PMID 21689422, 2011). "Previously, receptor tyrosine kinase genomic alterations were detected in 20.6% of cases, affecting ERBB2, FGFR2, and MET, suggesting potential benefit from targeted therapy including MET-amplified gastric tumors and ERBB2 base substitutions." (PMID 27384994, 2016). "Integrated analysis of public data from gastric tumors revealed frequent (10 – 20 %) amplification of the genes NFKBIE, PTK2, and PIK3CA, each of which resides in an ERBB2-derived subpathway network." (PMID 26955870, 2016). "If we apply the breast or gastric IHC scoring system to our non-breast/non-gastric tumor samples, an ERBB2 estimated CN gain of 8 or more (estimated CN ≥ 8) would be equivalent to an IHC3 + score (90% sensitivity and 75% specificity)." (PMID 33710417, 2021). "Using mass spectrometry-based genotyping we analysed 105 hotspot, non-synonymous somatic mutations in PIK3CA and ERBB-family (EGFR, ERBB2, ERBB3 and ERBB4) genes in gastric tumour samples from 69 patients." (PMID 33933113, 2021). "At this time, assignment to one of four molecular classes does not appear to add value beyond the features already actionable for clinical decision-making in gastric tumors (e.g. carcinoma vs gastrointestinal stromal tumor, ERBB2 (HER2) gene amplification in metastatic carcinoma, stage)." (PMID 25613731, 2015). "However, Both ERBB2 and EGFR gene amplification of gastric tumors were 3 cases (4.3%), but abnormalities both ERBB2 and EGFR gene copy number were present in 36.2% of samples." (PMID 21689422, 2011).
ductal carcinoma (154 papers, 2006 to 2025). "ERBB2 mutations are uncommon (2.2%) and mostly identified in ductal carcinoma." (PMID 33732635, 2020). "Invasive ductal carcinomas were distributed among all subclusters, but entirely dominated the highly proliferating luminal, basal-like and ERBB2+ groups." (PMID 17504517, 2007). "In addition to the histologic resemblance, SDC is similar to breast ductal carcinoma regarding overexpression of ERBB2 and EGFR in many cases." (PMID 25343854, 2014). "Nevertheless, the obtained results suggest that a high percentage of ERBB2-overexpressing ductal carcinomas may express KLF6 at the nuclear compartment during early stages of development." (PMID 20126619, 2010). "Invasive ductal carcinoma was more likely to be ERBB2 positive, which could influence outcomes." (PMID 37938845, 2023). "Also, expression of oncoproteins with anti-apoptotic activities, including receptor tyrosine kinase ErbB2, colony-stimulating factor 1 receptor, SRC, and IGF1R, has been shown to elicit abnormal, filled phenotypes that resemble human ductal carcinoma in vivo." (PMID 20043854, 2009). "In contrast, ERBB2-negative ductal carcinomas showed a significant lower KLF6 stain scores (p = 0.007; student t test) and absence of nuclear staining compared to ERBB2-overexpressing ductal carcinomas (score mean 1.9 versus 2.5, respectively)." (PMID 20126619, 2010).
esophageal cancer (153 papers, 2005 to 2025). A primary or metastatic malignant neoplasm involving the esophagus. "Hoffmann38 proposed a diagnostic method to detect ErbB2 amplification in single disseminated cancer cells, demonstrating that ErbB2 amplification in esophageal cancer patients is significantly correlated with short-term survival." (PMID 32728182, 2020). "In our study, the disrupted ERBB pathway including mutation in ERBB2 (35%), which can be used to explore the TKIs therapy in esophageal cancer." (PMID 29370817, 2018). "In esophageal cancer models, we found that ERBB2 amplification is associated with MASTL and NEK9 KGDs." (PMID 26947069, 2016). "The copy number variation of erbB2 gene from plasma can be used as prognostic marker for early detection of patients at risk of worse clinical outcome in esophageal cancer." (PMID 21481261, 2011). "The association of erbB2 CN and the clinical features of the esophageal carcinoma were also assessed by the Chi-Squared Test." (PMID 21481261, 2011). "Tumors with high levels of ERBB2 amplification (>20 copies), were also significantly more common in patients with breast (7.06%) and esophageal cancers (10%) than urothelial cancers (2.93%) (p < 0.001)." (PMID 41422272, 2025). "The downregulation of miR-375 contributes to ERBB2-mediated VEGFA overexpression in esophageal cancer." (PMID 37397256, 2023). "This receptor tyrosine kinase is upregulated in 10–20% of esophageal squamous cell carcinoma (ESCC) tissues, and amplification of ERBB2 has been correlated with poor prognosis in esophageal cancer." (PMID 27203740, 2016). "The real-time PCR assays for erbB2 gene showed significant (P = 0.001) copy number variations in the plasma of patients with esophageal carcinoma, as compared to healthy controls with high sensitivity (80%) and specificity (95%)." (PMID 21481261, 2011). "The GRB7 and ERBB2 genes are co-amplified and/or overexpressed in human gastric and esophageal carcinoma cell lines, and in primary gastric and esophageal cancers, particularly within the lower segment of the esophagus." (PMID 19424485, 2008). "However, in certain cancers, including breast, ovarian, bladder, pancreatic, stomach, and esophageal cancers, overexpression of the ERBB2 protein occurs." (PMID 41150737, 2025). "ErbB2 is a well-established therapeutic target whose overexpression occurs in various solid tumors, including—but not limited to—breast, gastric, ovarian, colon, bladder, lung, uterine cervix, head and neck, and esophageal cancers." (PMID 36140319, 2022). "For example, ERBB2-mutant NSCLC were shown to preferentially internalize the HER2 receptor antibody–drug conjugate complex, and this has led to new studies in ERBB2-mutant solid tumors (which include gastric and oesophageal cancers, as shown here)(NCT04639219)." (PMID 34794033, 2021). "Hence, ERBB2 is considered a potential therapeutic target for esophageal cancer." (PMID 27203740, 2016). "Lastly, esophageal cancer often exhibits intrachromosomal amplification of MYC, ERBB2, EGFR, RB1, GATA4/6, CCND1, RTK and MDM2 as well as ecDNA-associated amplification of MYC and MDM2." (PMID 41415205, 2025). "Biomarkers, such as Epidermal Growth Factor Receptor, Erb-B2 Receptor Tyrosine Kinase 2 (HER2), and Vascular Endothelial Growth Factor Receptor, have all been reported in oesophageal cancer." (PMID 37835435, 2023).
esophageal cancer (continued). "For example, approximately 45% of driver events in esophageal cancer included focal amplifications in cell cycle genes such as CCND1/2/3 and CDK4/6/9, in addition to amplifications in ERBB2, KRAS, MYC." (PMID 33889297, 2021). "In both breast and esophageal cancer, t-DARPP physically interacted with ERBB2 in a protein complex to mediate trastuzumab resistance." (PMID 29782621, 2018). "An enhanced expression of human epidermal growth factor receptor 2 (HER2, ErbB2) often occurs in an advanced stage of breast, ovarian, gastric or esophageal cancer, and pancreatic ductal adenocarcinoma (PDAC)." (PMID 29725336, 2018). "Chromosomal aberrations leading to gene dysregulation have been reported in esophageal cancer including amplifications on 8q and 17q mapped to the C-MYC and ERBB2 oncogenes." (PMID 25784931, 2015). "Moreover, the mRNA expression of ERBB2 exhibited a positive correlation with CNV in 88 TCGA-EAC patients in the cBioportal for Cancer Genomics, as well as in 974 cancer cell lines, and 27 esophageal cancer cell lines in the CCLE database." (PMID 34252349, 2021). "Additionally, a gold nanoprobe labeled with a heterobivalent (HB) peptide ligand, HB-Au-NPs, has demonstrated good results in esophageal cancer imaging, where it can specifically target overexpressed epidermal growth factor receptor (EGFR) and tyrosine kinase receptor 2 (ErbB2) in cancer cells." (PMID 38026877, 2023). "Amplified genes were noted in 37% of gastric/esophageal tumors, including ERBB2, FGFR1, FGFR2, EGFR, and MET, suggesting that some of these may be viable targets in esophageal cancer although amplification of some of these may be more prevalent in gastric tumors." (PMID 25784931, 2015). "The mRNA expression of ERBB2 had a significantly negative correlation with DNA methylation in 88 TCGA-EAC patients in cBioportal for Cancer Genomics database and in the whole 831 cancer cell lines but not 20 esophageal cancer cell lines in CCLE database." (PMID 34252349, 2021).
sarcoma (152 papers, 2012 to 2025). A usually aggressive malignant neoplasm of the soft tissue or bone. "SDUS may be susceptible to EZH2 or CDK4/6 inhibition, and early evidence suggests that ERBB2/3-mutated S100/SOX10-positive sarcomas may benefit from HER2-targeted therapy." (PMID 41463261, 2025). "First clinical evaluations of ErbB2-directed CAR-T cells for sarcomas have proven the safety and feasibility of this approach but had limited efficacy." (PMID 39963129, 2025). "Several types of sarcoma express ErbB2 (HER2) at low levels, rendering this receptor tyrosine kinase a potential target for immunotherapy." (PMID 39963129, 2025). "A very similar CD28-CD3ζ CAR harboring the same FRP5-derived single-chain fragment variable antibody domain has been safely employed in phase I/II CAR-T clinical trials in pediatric patients with ErbB2+ sarcoma." (PMID 39963129, 2025). "BRAF and ERBB2 mutations, however, specifically BRAF V558E and ERRB2 V659E, are depleted in sarcoma." (PMID 37414794, 2023). "The safety of treatment with ERBB2-specific autologous CAR-T cells was initially demonstrated in a phase I/II clinical trial in sarcoma patients at Baylor College of Medicine, Houston, Texas, USA." (PMID 33809981, 2021). "Exposure of sarcoma cells to [pazopanib + entinostat] caused activation of ERBB1, ERBB2, c-KIT, c-MET, and c-SRC." (PMID 31380285, 2019). "Exposure of sarcoma cells to [pazopanib + entinostat] caused activation of ERBB1 and c-SRC and in a cell-specific fashion, activations of ERBB2, c-KIT, and c-MET." (PMID 31380285, 2019). "Both BIRC5 and ERBB2 genes generated a significant result with P-value < 2.2e-16 in both TCGA sarcoma and uterine corpus endometrial carcinoma." (PMID 29459674, 2018). "ErbB2 induces malignant transformation and tumorigenesis in NIH 3T3 fibroblasts, indicating that ErbB2 functions as an oncogene that is also correlated with a poor prognosis in malignancy, e.g., in sarcoma." (PMID 29029499, 2017). "Positive expression of cyclin D1 and ErbB2/HER2 were seen in 44 cases (57.9%) and 0 case (0%) of sarcomas, respectively." (PMID 27249072, 2016). "The 4 highest IL-2 secretor clones identified in this initial screen were then selected for further analysis and cultured with anti-c-myc antibody or the sarcoma cell line 24JK transfected to express erbB2 or controls, and IL-2 secretion determined." (PMID 23667569, 2013). "However, several pan-cancer immunotherapy target antigens, including B7-H3/CD276, GD2 and Erbb2/HER2/neu were markedly upregulated in sarcoma GEMMs." (PMID 40523919, 2025). "At present, ACT is mostly carried out in hematological malignancies, while CAR-T cell technology has also been conducted in sarcoma targeting ERBB2/HER2, renal cell carcinoma targeting carbonic anhydrase, and cholangiocarcinoma targeting epidermal growth factor." (PMID 36387286, 2022). "In a phase I/II clinical trial, ERBB2-CAR T cells persisted for 6 weeks but ultimately failed to improve the outcome of high-risk sarcoma patients." (PMID 33193388, 2020). "EGFR and ERBB2 activation in LNCaP cells under the influence of osteoblast-derived sarcoma cells (OHS) has been reported to activate EGFR/ERBB2 signaling pathways in LNCaP cells co-cultured with osteoblastic cells that had been differentiated from human mesenchymal stem cells or OHS cells." (PMID 31137764, 2019). "Also, the expression of ADC targets including ERBB2/HER2 in sarcomas remains underreported, preventing the development of ADCs such as T-DXd in this rare and heterogeneous family of tumours, whereas their use could represent a major therapeutic opportunity." (PMID 39921935, 2025). "In addition, as neratinib blocks both ERBB2 and Ezrin phosphorylation, this drug may have particular utility in sarcomas." (PMID 31380285, 2019). "Among the five sarcomas, only DSRCT showed relatively high mRNA expression of both EGFR (top) and ERBB2 (bottom), supporting a potential role for the ERBB family receptors in DSRCT growth." (PMID 34841430, 2022).
sarcoma (continued). "We also performed a t-test analysis for each BIRC5, ERBB2 and EZH2 in TCGA sarcoma, uterine corpus endometrial carcinoma and ovarian serous cystadenocarcinoma." (PMID 29459674, 2018). "Ongoing trials target mesothelin, ErbB2/Her2, GD2 (neuroblastoma or sarcoma), or GPC3 (hepatocellular carcinoma)." (PMID 28765140, 2017). "Currently, no data are available about the activity of ErbB2- or directly ErbB3-targeted therapy in pediatric sarcoma." (PMID 23227212, 2012). "The gene expression analysis demonstrated a consistent high RNA expression level of ERBB2 in DSRCT, with elevated levels [>5 log2(transcripts per million + 1)] across all samples of the cohort and the expression level was the highest compared with all other sarcoma subtypes." (PMID 39921935, 2025). "Most metaplastic (64.0%) and medullary (50.2%) cancers and sarcomas (67.8%) were ERBB2 negative." (PMID 36821125, 2023). "In addition, the gene expression analysis demonstrated a high RNA expression level of ERBB2 in DSRCT, with elevated levels [>5 log2(transcripts per million + 1)] across all samples of the cohort and the expression level was the highest compared with all other sarcoma subtypes." (PMID 39921935, 2025). "Although crosstalk between different signalling cascades are not uncommon in cancer cells, a connection between ERBB2/HER2 and FGFR signalling in sarcoma cells has not yet been established and its functional consequences are not yet clear." (PMID 38177929, 2024).
invasive carcinoma (144 papers, 2005 to 2026). A carcinoma that is not confined to the epithelium, and has spread to the surrounding stroma. "We established a model where acquisition of phenotypes that resembled DCIS or invasive carcinoma can be mimicked by expressing the Wt-ErbB2 and a CA-ErbB2, respectively." (PMID 19754954, 2009). "In keeping with diagnostic anatomo-pathological experience, the relative expression of ERBB2, ESR1, PGR and MKI67 in our study was often higher in DCIS samples than in samples enriched for invasive carcinomas." (PMID 30342538, 2018).